TERT (telomerase reverse transcriptase)
Diseases named in the same sentence as TERT in open-access papers (continued):
Sharing a sentence is not in itself a finding about the gene and the disease.
breast carcinoma (continued). "TERT gene gains were associated with higher TERT mRNA expression in non-small-cell lung adenocarcinoma and Merkell cell carcinoma and with high TERT protein expression in breast cancer and cervical carcinomas." (PMID 29100407, 2017). "Our observation of a highly positive correlation between the TERT gene copy number and its mRNA level suggests that TERT gain has a functional effect on TERT transcription in breast cancer." (PMID 29100407, 2017). "The ratio between wild type and β-spliced TERT was found to determine the level of telomerase activity (TA) in 50 breast cancer cell lines." (PMID 27322326, 2016). "To examine the effects of rapamycin on TERT shuttling from nucleus to mitochondria in vitro, we first treated TERT-positive MCF-7 human breast cancer cells with rapamycin for 3 days." (PMID 27777385, 2016). "A study using human reduction mammary fibroblasts immortalized with h-TERT also found increased levels of proliferation restricted to the Luminal breast cancer cell subtype." (PMID 25274034, 2014). "The current analyses suggest that 10 loci are now known to be associated with breast cancer risk for BRCA1 mutation carriers: 1q32, 10q25.3, 19p13, 6q25.1, 12p11, TOX3, 2q35, LSP1 and RAD51L1 all reported here and TERT." (PMID 23544013, 2013). "We show that in breast cancer cells, TERT downregulation with low doses of specific siRNA induces apoptosis." (PMID 23677713, 2013). "We confirmed the association of four SNPs representing three previously reported susceptibility loci with breast cancer risk among Polish women: FGFR2 (rs1219648 and rs2981582), TERT (rs2736098) and 8q24 (rs13281615)." (PMID 24171766, 2013). "To look more specifically at BRCA1-dependent regulation of the Notch receptors and ligands in the normal breast, we used two pseudo-normal breast cancer cell lines—HME-1 h-TERT immortalized cells and spontaneously immortalized 184A1 cells." (PMID 23863842, 2013). "We report here that targeting TERT can down-regulate telomerase activity and inhibit proliferation of breast cancer cells in vitro, suggesting the potential for therapy." (PMID 23677713, 2013). "Beside rs2736098 in TERT, only the association of rs3731249 in CDKN2A was analyzed previously and significant correlation was identified for early-onset breast cancers." (PMID 24171766, 2013). "Both rs10069690 at 5p15/TERT and rs999737 at 14q24/RAD51L1 showed the strongest association for ER−/PR−/HER2− breast cancer though associations were also observed for ER+ and ER− cancers." (PMID 23593120, 2013). "We performed a case-control study to evaluate the role of three SNPs (TERT-07, TERT-54 and POT1-03) in telomere maintenance genes previously found to be significantly associated with breast cancer risk." (PMID 22970196, 2012). "We previously identified three genetic variants in telomere maintenance genes (TERT and POT1) that were significantly correlated with breast cancer risk in a large (1,067 cases, 1,110 controls) case-control study, the Long Island Breast Cancer Study Project." (PMID 22970196, 2012). "The present study indicates that a reduction in SFRP1 expression allows 76 N TERT cells to acquire many of the properties observed in breast cancer cells." (PMID 19422694, 2009). "In breast cancer, a reduction in TERT methylation levels in cfDNA has been observed following effective treatment, suggesting that cfDNA analysis could serve as a potential biomarker for monitoring therapeutic efficacy in the future." (PMID 39871386, 2025). "CTD-3080P12.3, also known as TERLR1, is located at a well-known breast cancer risk locus (lead variant rs2853669, also known as the TERT SNP), however, this gene has not been reported in association with breast cancer in any previous studies." (PMID 38697998, 2024).
breast carcinoma (continued). "In cells grown in 3D, progestins regulate a group of breast cancer-associated genes that are also regulated in 2D including CDH10, PGR, CHEK2, LSP1, TERT, SDPR, but also a new set of 3D-exclusive genes, associated to the ECM including members of the integrin family, Laminins, and AKT3." (PMID 38565950, 2024). "The hotspot mutations of TERT promoter C228T and C250T appeared to be a rare event in breast cancer with a frequency <0.9% depending on the series and no prognostic correlation has been established so far." (PMID 39090361, 2024). "The rs10069690 single nucleotide variant, located in intron 4 of TERT, was found to be associated with telomere length and the risk of estrogen receptor-negative but not–positive breast cancer." (PMID 36768147, 2023). "In addition, functional studies are necessary to reveal the role of the TERT rs10069690 genotypes in breast cancer development and progression." (PMID 36768147, 2023). "In general, however, TERT expression levels were considerably elevated in breast tumors and breast cancer cell lines compared to healthy controls, consistent with the finding that TERT expression is silenced in differentiated adult tissues but reactivated in most tumors." (PMID 36768147, 2023). "Accordingly, rs10069690 was genotyped in a hospital-based case-control study of 403 female breast cancer patients and 246 female controls of a Central European (Austrian) study population, and the mRNA levels of TERT were quantified in 106 primary breast tumors using qRT-PCR." (PMID 36768147, 2023). "Importantly, breast cancer has a very low frequency of TERT promoter mutation, which implies epigenetic regulation in this type of cancer and possibly a wider systemic effect, especially in HER2-positive breast cancer." (PMID 36361634, 2022). "Upregulation of TERT resulting in increased telomerase activity may, in part, explain the poor prognoses identified in this study and previously in breast cancer." (PMID 36497424, 2022). "Variants in TERT-CLPTM1L showing no relation to breast cancer risk in meta-analyses with at least 5000 cases and 5000 controls in additive model." (PMID 35847915, 2022). "In addition, four cytokeratin genes (KRT8, KRT16, KRT17, and KRT19) and eight tumor-associated genes (TERT, MUC16/M17S2/CA125, CD44, TWIST1, TACSTD1/EpCAM/CD326/ESA/HEA125/GA733, DPP4/CD26, ESR1, and PGR), were upregulated in CRC and breast cancer samples." (PMID 29882767, 2018). "Our results from a total of 122 breast tumors evidenced no TERT promoter mutations, suggesting that this mutational mechanism is not likely to be involved in TERT upregulation in breast cancer." (PMID 29100407, 2017). "Some common genetic variants of TERT-CLPTM1L are hypothesized to have an important role in initiation and development of many cancers, including lung, bladder, pancreatic, thyroid, and breast cancer." (PMID 29254260, 2017). "Our results suggested that genetic variants in TERT significantly increased the risk of lung cancer, bladder cancer, breast cancer, colorectal cancer and other cancer, but not HCC and SCCHN." (PMID 29221218, 2017). "ETS2 is important for driving TERT gene expression and breast cancer cell proliferation." (PMID 28184371, 2017). "No activating TERT promoter mutations were found, suggesting that this mutational mechanism is not likely to be involved in TERT upregulation in breast cancer." (PMID 29100407, 2017). "In population-specific analysis, the GWAS index SNP rs10069690 in the TERT gene was significantly associated with ER− breast cancer in African Americans (p = 1.11 × 10−6) but in no other population (all p > 0.3)." (PMID 27814745, 2016).
breast carcinoma (continued). "TERT mRNA expression significantly correlates with telomerase activity in human breast cancer." (PMID 23677713, 2013). "As we demonstrated in breast cancer cells, TERT downregulation seems to be the most efficient." (PMID 23677713, 2013). "The expression of vimentin may be mediated by β-catenin in TERT-siSFRP1 cells since β-catenin can transactivate vimentin in breast cancer cells and β-catenin activity is enhanced in TERT-siFRP1 cells." (PMID 21303533, 2011). "Similarly, the prognostic role of TERT promoter methylation had been reported in several other types of cancer, including childhood brain tumors, pancreatic cancer, bladder cancer, and breast cancer." (PMID 38313800, 2024). "Moreover, since it co-purifies with TERC and dyskerin in the presence of TERT, and its expression correlates positively with telomerase activity both in vitro and in clinical breast cancer samples, PES1 may make contact with the telomerase RNP." (PMID 32599885, 2020). "However, TERT mutation is not universal and has been absent, or rarely observed, in some cancer types such as breast cancer, prostate cancer, thymic tumor, histiocytosis, and mature T and NK neoplasms." (PMID 32810393, 2020). "Our findings show that the known driver mutations in the TERT promoter do not commonly occur in breast cancer, but TERT is frequently overexpressed in breast tumors and this altered expression is associated with mutations in the putative driver DHS (chr5:1325957-1328153)." (PMID 28874753, 2017). "For the first time, we show that TERT gain is also a negative prognostic marker associated with higher risk of disease recurrence or death from breast cancer and could potentially be used to adapt treatment strategies." (PMID 29100407, 2017). "In conclusion, we found no activating TERT promoter mutations in 122 breast cancer patients." (PMID 29100407, 2017). "Beyond telomerase enzymatic activity, TERT mRNA expression level has been studied as biomarker, because it has been demonstrated to be the rate-limiting determinant of telomerase activity in various malignancies, such as urothelial cancer, non-small cell lung cancer, and breast cancer." (PMID 27240403, 2016). "Cell lines from different tissue types fibrosarcoma (HT1080), colon cancer (HCT116), and breast cancer (MDA-MB-231), engineered for either telomere elongation/shortening, gave an increase/decrease in TERT, respectively." (PMID 41026782, 2025). "Telomerase reverse transcriptase (TERT) has a well-known role in carcinogenesis and, together with ITGA6, is recognized as a stem cell marker in breast cancer cell lines and has been described as having a substantial direct association with malignant tissue." (PMID 37444576, 2023). "Our previous study successfully constructed coding sequence optimized GST-TERT and identified that PES1, which expression elevated in many cancers, promoted assembly of TERT and TERC in breast cancer cells." (PMID 35669414, 2022). "In order to determine the mechanism governing the regulation of CSC by piR-823 in breast cancer cells, stem cell-regulating factors including OCT4, SOX2, KLF4, NANOG, and h-TERT were examined in MCF-7 cells after knockdown or overexpression of piR-823." (PMID 33791297, 2021). "The inverse relationship between SLX4IP and TERT was conserved in both TNBC and HER2+ breast cancers, and these aberrations manifested specifically during metastasis to the CNS." (PMID 32071280, 2020). "In breast cancer cells, MYC binds to an ETS2 site (EtsA) in the TERT gene promoter and increases TERT expression levels." (PMID 29100407, 2017). "By combining the data on TERT gain and MYC overexpression we were able to isolate a particularly bad prognosis subgroup of breast cancer patients." (PMID 29100407, 2017).
breast carcinoma (continued). "To address these issues, we investigated the mutational status and genotype of the TERT promoter, TERT gene copy number and TERT and MYC mRNA expression in two breast cancer cohorts." (PMID 29100407, 2017). "The aim of the study was to analyze the consequence of silencing genes coding for the key subunits of the telomerase complex, i.e. TERT, TERC and TP1 in human breast cancer MCF7 and MDA-MB-231cells." (PMID 23677713, 2013). "In a population-based study of 1995 breast cancer cases and 2296 controls from Poland, 24 SNPs representing common variation in POT1, TEP1, TERF1, TERF2 and TERT were genotyped." (PMID 17848914, 2007). "We have created a new model for ERα-positive breast cancer by transduction of normal HMECs with lentiviruses expressing ERα, BMI1, MYC and TERT." (PMID 17573968, 2007). "(A) Key Immune marker expression (TAM markers, TAM related chemokines, T cell markers), TERT and TERC were plotted for fold change of transcript level expression (IL1R1 high / IL1R1 low) and adjusted p-values in breast cancer (BRCA) samples categorized as IL1R1 high or low from TCGA." (PMID 39728924, 2024). "Relative TERT mRNA expression levels were determined in breast cancer (n = 15) and normal (non-tumor) breast cell lines (Hs 578Bst, MCF-10A, MCF-10F, and HMEC; n = 4)." (PMID 36768147, 2023). "We have previously demonstrated that LRP levels are directly associated with telomerase activity, in that LRP overexpression significantly increases the TERT levels and telomerase activity, and the downregulation of LRP/LR significantly decreases the telomerase activity in breast cancer cells." (PMID 36579897, 2023). "Of note, benefit by TERT in B high tumors was also observed in non-TNBC breast cancer (P = 0.044) whereas a trend toward the opposite effect on clinical course was found in GBM (P = 0.165)." (PMID 36909826, 2023). "The 15 breast cancer cell lines expressed TERT at ≈75-fold higher mean levels than the three non-tumor cell lines (median, ≈275-fold; p = 0.015, Kruskal-Wallis test)." (PMID 36768147, 2023). "It has been reported that PUF60 has tumor promoting effects in breast cancer 49, but it remains to be investigated whether this effect of PUF60 depends on TERT signaling." (PMID 33061812, 2020). "Unlike in breast cancer and lung cancer, TERT shows increased expression levels in group 2 of colon cancer samples, which is associated with the lower survival rate of group 2 of colon cancer samples." (PMID 31856825, 2019). "CCNB1 has been known to be associated with breast cancer, but so far there is little or no direct relation known between CCNB1 and TERT." (PMID 31856825, 2019). "To investigate these mechanisms in breast cancer, we sequenced the TERT promoter, evaluated TERT copy number changes and assessed the expression of the MYC oncogene, a known transcriptional TERT regulator, in two breast cancer cohorts comprising a total of 122 patients." (PMID 29100407, 2017). "For example, it has been recently demonstrated that the β-spliced TERT protein without any catalytic activity promoted cellular growth and was able to protect from cisplatin-induced apoptosis in breast cancer cells." (PMID 27322326, 2016). "Further analysis of genes associated with breast cancer, including ABCB1, BRCA1, GSTP1, IGF2, and TERT, showed a high CM fraction in cancer but non-CM in normal cell lines." (PMID 26659027, 2015). "Nevertheless, there was lack of association between common single nucleotide polymorphisms in the TERT-CLPTM1L locus and breast cancer in non-Hispanic whites." (PMID 23738012, 2013).
breast carcinoma (continued). "Within human breast cancer cell lines, expressions of TRF1, TIN2, and POT1 are upregulated by dexamethasone, suggesting activation of the glucocorticoid receptor, whereas TERT, TRF2, TRF1, TIN2, and POT1 are upregulated by TNF-α, suggesting activation of the NFκB transcription factor." (PMID 23342266, 2012). "The TT genotyping of TERT-54 and AA genotyping of POT1-03 were inversely associated with breast cancer risk but the associations were not statistically significant (the ORs were 0.83 (95%CI: 0.44–1.57) and 0.48 (95%CI: 0.23–1.00), respectively)." (PMID 22970196, 2012). "When SFRP1 is knocked down in immortalized non-malignant mammary epithelial cells, the cells (TERT-siSFRP1) exhibit a malignant phenotype which resembles the characteristics observed in metastatic breast cancer cells." (PMID 21303533, 2011). "In summary, our data demonstrate that 76N TERT cells express RAR, RXR, ER and PR, and represent a potential useful model to investigate the genetic changes, and the carcinogenic or chemopreventive effects of new agents on the development of mammary tumors." (PMID 15755327, 2005). "The chosen cell lines included normal human mammary epithelial cells derived from primary tissue and immortalised with TERT expression (hMEC-TERT), 6 basal-like (HCC-70, BT-549, BT-20, MDA-MB-231, MDA-MB-436, MDA-MB-468) and 4 luminal-like (BT-474, MCF-7, T47D, MDA-MB-361) breast cancer cell lines." (PMID 24967588, 2014). "For example, although telomerase is expressed in >85% of human cancers, including breast cancers, the levels of telomerase reverse transcriptase (TERT) mRNA are not correlated with telomere length and can differ more than 700-fold in human breast cancer tissues." (PMID 23342266, 2012). "Using data from a large population-based case-control study, we previously identified three genetic variants (TERT rs2736109, rs3816659 and POT1-03 rs33964002) in telomere maintenance genes associated with breast cancer risk, but no independent data has validated this finding." (PMID 22970196, 2012). "Because our hypothesis is that TERT gene disruption may offer a universal approach to treat cancer, we selected three different cancer cell lines to evaluate the efficiencies of these gRNAs: a cervical cancer cell line Hela, a pancreatic cancer cell line PANC1, and a breast cancer cell line SUM159." (PMID 31963842, 2020). "Unlike the tumor cell lines widely used in breast cancer researches such as MCF-7 and MDA-MD-231 cells, which have undergone several steps in tumorigenesis, the 76N TERT cell line represents a system that is immortal but does not yet have the capacity to form a tumor." (PMID 15755327, 2005).